ENPP1 (ectonucleotide pyrophosphatase/phosphodiesterase 1)
Diseases named in the same sentence as ENPP1 in open-access papers (continued):
Sharing a sentence is not in itself a finding about the gene and the disease.
tumor (continued). "Many tumors secrete cGAMP in the tumor microenvironment but, interestingly, cGAMP efflux from cancer cell lines can only be observed upon chemical inhibition or knockdown of ENPP1." (PMID 37287967, 2023). "Building on our findings that ENPP1 catalytic activity alters the composition of the tumor immune compartment, we next investigated its impact on the functional landscape of tumor-infiltrating immune cells." (PMID 38117852, 2023). "Tumor resistance is also observed in mice treated with ENPP1 inhibitors, an effect enhanced by simultaneous radiotherapy, a treatment known to increase erroneous chromosomal segregation and so augmenting detection of self-DNA by cGAS." (PMID 37287967, 2023). "Prior studies have shown that knockdown of ENPP1 can reduce metastasis, induce cell death, and enhance tumor responsiveness to immune checkpoint therapy." (PMID 36761762, 2023). "Ectonucleotide pyrophosphatase/phosphodiesterase 1 (ENPP1) codes a transmembrane protein upregulated in many cancers, suppresses the innate immune response, and promotes tumor cell migration, proliferation, metastasis, and angiogenesis." (PMID 38435029, 2023). "ENPP1 promoted neutrophil extracellular trap (NET) formation via tumor cell expression of haptoglobin, supporting relapse and protecting the tumor from radiotherapy." (PMID 36910138, 2023). "The importance of cancer- and responder-cell-derived ENPP1 in tumor development is in line with our understanding of paracrine extracellular cGAMP signaling as being short-ranged." (PMID 38117852, 2023). "Overall, our work provides a strategy for the development of a promising drug candidate targeting ENPP1 for tumor immunotherapy." (PMID 35806118, 2022). "Among these inhibitors, STF-1084 displayed a Ki value of 33 nM against ENPP1, which delays tumor growth in cancer models owing to an increase in the level of endogenous cGAMP." (PMID 35806118, 2022). "This suggests that with the increase of ENPP1 expression, the invasion and metastasis of cancer cells spread faster, the tumor cell differentiation is poorer." (PMID 33635867, 2021). "Recent studies have shown that the expression of ENPP1 is related to differentiation, death, dissemination and chemosensitivity of tumor cells." (PMID 33635867, 2021). "There were no cases of strong expression in patients with stage I. At the same time, we found that with the decrease of tumor cell differentiation, the number of cases with strong ENPP1 expression gradually increased." (PMID 33635867, 2021). "SR-8314 and SR-8291 are both highly selective ENPP1 inhibitors that have shown promising in vivo efficacy in syngeneic murine tumor models." (PMID 34070756, 2021). "SR8541A is another small molecule ENPP1 inhibitor which in recent in vitro studies has been shown to stimulate the migration and infiltration of peripheral blood myeloid cells into the tumor microenvironment." (PMID 34070756, 2021). "Recent studies of the cGAS-STING pathway in anti-tumor immunity have demonstrated that cGAMP can be released into the extracellular space where its lifespan is regulated by ENPP1, a cell surface phosphodiesterase that hydrolyzes cGAMP to AMP and GMP30." (PMID 32404939, 2020). "ENPP1 expression is heightened in M2 macrophages in the presence of cancer and promotes tumor growth and spread." (PMID 31752288, 2019). "ENPP1, as a highly potent cGAMP-degradation enzyme, makes the application of ENPP1 inhibitors for anti-tumor therapy a very topical issue." (PMID 31752288, 2019). "These translational studies represent a novel approach to enhancing tumor directed immune response following radiation, and provide a foundation for clinical development of an ENPP1 inhibitor as a cancer immunotherapy." (PMID 30400822, 2018). "We demonstrate for the first time that, in combination with radiation therapy, ENPP1 inhibition improves outcomes and cures tumors in preclinical models through changes in the tumor immune environment." (PMID 30400822, 2018).
tumor (continued). "Recently, a study have identified that miR-27b-3p (also known as miR-27b) functioned as a tumor suppressor to inhibit breast cancer stem cell generation by inactivating ENPP1, to attenuate chemoresistance and tumor seeding ability." (PMID 29416005, 2018). "Next, we examined the tumour seeding ability of ENPP1 knockdown MCF7-luc cells (MCF7-luc shENPP1 cells) using 5-week-old NOD/SCID mice." (PMID 26065921, 2015). "ENPP1 induced the generation of a SP fraction that had tumour seeding ability and was resistant to conventional chemotherapy by promoting the expression and cell surface localization of ABCG2." (PMID 26065921, 2015). "In vivo imaging revealed that tumour development occurred in all three mice and ENPP1 expression was detected in approximately 5% of the tumour cells." (PMID 26065921, 2015). "Tumor PZP had a 12.5 kb inverted insertion originating from chromosome 6 containing ENPP1 exons 19 to 25 including the stop codon." (PMID 25762628, 2015). "Moreover, tumor-derived exosomes and the surface enzyme ENPP1 can hydrolyze extracellular cGAMP, thereby disrupting paracrine STING signaling and generating adenosine, which suppresses antitumor immunity and promotes tumor metastasis." (PMID 41415288, 2025). "It has been reported that Enpp1 promotes the chemotactic infiltration of polymorphonuclear marrow-derived inhibitory cells and suppress the tumor-infiltrating cytotoxic T cells preventing anti-tumor immune attack on breast cancer cells." (PMID 39972484, 2025). "Consequently, tumor-derived exosomal ENPP1 modulates immune responses by hydrolyzing cGAMP to inhibit cGAS-STING signaling." (PMID 40103824, 2025). "In a model of local recurrence (LR), circulating tumor cells (CTC) engrafting in the post-resection tumor bed developed a radioresistant phenotype linked to an ENPP1+-gene signature which was also identified in TNBC patients, suggesting ENPP1 ́s role in genome integrity." (PMID 40506449, 2025). "Enpp1 can also be expressed by immune cells in the tumor environment." (PMID 39622844, 2024). "Blocking macrophage phagocytosis has resulted in improved tumor control over a range of targets and tumor models, and our data suggests that Enpp1 inhibition may be a general strategy to improve tumor immunogenicity and radioimmunogenicity." (PMID 39622844, 2024). "Importantly, the expression level of tumor exosomal ENPP1 shown an inverse correlation with CD8+ T cells and CD4+ T cells infiltration, respectively." (PMID 38498770, 2024). "This suggests that ENPP1 may exist in other forms in the tumor microenvironment, in addition to its membrane‐bound form on tumor cells." (PMID 38498770, 2024). "The combination of chemotherapy drugs and ENPP1 inhibitors may have special advantages for tumor treatment." (PMID 38498770, 2024). "ENPP1 is expressed and secreted by normal tissues and controls multiple physiological pathways, creating concerns for off-tumor toxicities and obstacles for on-tumor drug delivery." (PMID 37400538, 2024). "Moreover, exosomal ENPP1 from mouse tumor cells revealed inhibition of STING signaling in RAW‐Lucia ISG cells by hydrolyzed LL‐37‐2′3′‐cGAMP." (PMID 38498770, 2024). "Tumor cells upregulate ENPP1 on their surface as an immune evasion mechanism." (PMID 39295301, 2024). "Indeed, ENPP1‐OE EXOs showed a stronger capability to inhibit cGAS‐STING signaling than that of exosomes from WT tumor cells (inhibition rate 22.0% versus 12.4% in 24 h) due to the high expression of ENPP1." (PMID 38498770, 2024). "ENPP1 (Ectonucleotide Pyrophosphatase/Phosphodiesterase) is increasingly recognized as an important immune checkpoint in cancer immunobiology, playing a critical role in the modulation of the tumor microenvironment and immune evasion." (PMID 38881902, 2024). "Moreover, our study also demonstrates that tumor exosomal ENPP1 can hydrolyze endogenous 2′3′‐cGAMP produced by cells to inhibit cGAS‐STING pathway in bystander cells." (PMID 38498770, 2024).
tumor (continued). "Enpp1 expression may represent a general mechanism of inflammatory suppression in cancer therapy thereby expanding the range of tumors that can be treated by Enpp1 inhibition to tumor types where cancer cell expression of Enpp1 is rare." (PMID 39622844, 2024). "By precisely targeting ENPP1 on the cell surface, our hcAbs constitute a valuable tool for the detection of ENPP1 protein expression and may offer the potential to also target ENPP1-expressing tumor cells in vivo." (PMID 39694917, 2024). "ENPP3 expression pattern is distinct from that of ENPP1, and ENPP3 is more active at acidic pH than ENPP1, which might confer an advantage in an acidic tumor microenvironment." (PMID 39728440, 2024). "This stromal Enpp1 may be critical in blocking cGAMP reaching the immune cell rich tumor stroma where there is high hematopoietic cell expression of STING." (PMID 39622844, 2024). "Moreover, tumor exosomal ENPP1 disrupts 2′3′‐cGAMP transfer from paracrine tumor to bystander THP1‐Lucia ISG cells, which inhibited cGAS‐STING signaling in immune cells." (PMID 38498770, 2024). "When introducing STF‐1623 to the incubation process of 2′3′‐cGAMP and exosomes, although the ISRE reporter activity was enhanced, no activity change for control ADP was observed, which indicated that tumor exosomal ENPP1 inhibited cGAS‐STING pathway by hydrolyzing 2′3′‐cGAMP." (PMID 38498770, 2024). "Since ENPP1 is expressed by both tumor cells and immune cells, small molecule ENPP1 inhibitors could target this enzyme on both cell types, thereby potentiating STING signaling and its antitumor activities in both compartments." (PMID 38095464, 2024). "Moreover, tumor exosomal ENPP1 also can hydrolyze 2′3′‐cGAMP bound to LL‐37 (an effective transporter of 2′3′‐cGAMP) to inhibit STING signaling." (PMID 38498770, 2024). "In this context, the ENPP1 blockade of tumor‐derived exosomes could hold importance in immunotherapy." (PMID 38498770, 2024). "Therefore, in the case of LL‐37‐2′3′‐cGAMP, tumor‐derived exosomes only inhibit the cGAS‐STING pathway by hydrolyzing LL‐37‐2′3′‐cGAMP through ENPP1." (PMID 38498770, 2024). "Thus, Enpp1 represents a potentially important target to optimize innate immune activation in the tumor following radiation therapy." (PMID 39622844, 2024). "As expected, tumor exosomal ENPP1 overexpression reduced the extracellular 2′3′‐cGAMP level." (PMID 38498770, 2024). "In the present study we demonstrate that radiation causes cGAMP release, and that Enpp1 expression by non-cancer cells limits immune control of tumor by radiation." (PMID 39622844, 2024). "In contrast to small molecules, an antibody-based inhibitor of ENPP1 could be optimized for tumor cell selectivity by reformatting into multivalent constructs that recognize a second tumor-specific antigen." (PMID 37400538, 2024). "In addition, western blot results revealed that the level of exsomal ENPP1 was higher in tumor tissues than in paracancer tissues." (PMID 38498770, 2024). "Together, these results demonstrate that the ENPP1 blockade of tumor cells and tumor‐derived exosomes in the tumor microenvironment may be a promising antitumor strategy by innate immune regulation." (PMID 38498770, 2024). "In addition, we observed the hydrolytic capability of exosomal ENPP1 from mouse tumor cell lines to 2′3′‐cGAMP and LL‐37‐2′3′‐cGAMP." (PMID 38498770, 2024). "However, by comparing disparities A and B, we observed that lower concentrations of exosomes exhibited negative regulation of cGAS‐STING signaling due to tumor exosomal ENPP1‐dominated hydrolysis of 2′3′‐cGAMP." (PMID 38498770, 2024). "Based on our data we hypothesize that macrophages are the dominant cell type that express and secrete Enpp1 to limit locoregional STING activation in the tumor." (PMID 39622844, 2024).
tumor (continued). "Importantly, tumor control by radiation therapy combined with Enpp1 inhibition is dependent on STING and IFNAR1 expression in host cells, demonstrating that response functions via host sensing of cGAMP." (PMID 39622844, 2024). "Indeed, ENPP1 inhibitors were shown to delay tumor growth when used in combination with STING agonists." (PMID 38095464, 2024). "However, there is still evidence of hyperactive immune responses when ENPP1 is targeted systemically, underscoring the need to optimize the selectivity of ENPP1 inhibitors for tumor cells." (PMID 37400538, 2024). "Additionally, ENPP1 on healthy tissues and in plasma sequesters systemically administered inhibitors and interferes with the delivery of drug to tumor cells, affecting therapeutic potency and minimum dose concentrations." (PMID 37400538, 2024). "To determine whether tumor exosomal ENPP1 directly regulates the extracellular 2′3′‐cGAMP level, we measured the concentration of extracellular 2′3′‐cGAMP in cells co‐cultured for 24 h by 2′3′‐cGAMP ELISA Kit." (PMID 38498770, 2024). "Indeed, depleting cancer- or tissue-derived ENPP1 had an additive effect on slowing tumor growth, with tissue ENPP1 playing a larger role." (PMID 38117852, 2023). "Therefore, ENPP1 inhibition represents an exceptional therapeutic strategy as endogenous cGAMP production would then be localized to the tumor microenvironment." (PMID 37287967, 2023). "However, cancer cells also express ENPP1 which promotes metastasis by hydrolyzing extracellular cGAMP in the tumor microenvironment." (PMID 37287967, 2023). "In addition, recent studies indicate that ENPP1 is also involved in cGAS-STING signaling which plays an important role in the anti-tumor immune response." (PMID 36761762, 2023). "We hypothesize that ENPP1 also plays immunosuppressive roles in tumor types where either the cancer cells or the TME highly expresses ENPP1." (PMID 38117852, 2023). "Systemic treatment with ENPP1 inhibitors sidesteps clinical concern regarding tumor disruption during intratumoral injection of therapeutic CDNs, which may physically dislodge cancerous cells encouraging metastasis." (PMID 37287967, 2023). "Tumor cells can evade STING activation by expressing ENPP1 to degrade cGAMP." (PMID 36757811, 2023). "It has been reported that both genetic knockdown and inhibition of ENPP1 by small molecule could increase tumour-infiltrating DCs and decrease tumour growth." (PMID 36069240, 2022). "In summary, compound 4e, as a novel drug candidate targeting ENPP1, could regulate endogenous cGAMP and, thus, deserves further anti-tumor research in vivo." (PMID 35806118, 2022). "Hence, it seems likely that the tumor cells balance out the anti-tumor impact of the STING pathway by increasing ENPP1 expression, which also happens to induce metastasis." (PMID 36235254, 2022). "However, to confirm the levels of ENPP1, pan-cancer RNA and protein sequencing datasets from primary tumor tissue samples as well as cancer cell lines (CCLE datasets) were analyzed using cBioPortal and UALCAN analysis tools." (PMID 36235254, 2022). "Finally, we examined the gene expression of ENPP1 in an additional cohort of malignant PT (n = 14) relative to the MPT-S1 tumor sample." (PMID 35365682, 2022). "Our study not only validates the effect of ENPP1 inhibition in cell lines but also extends its effect in the 4T1 syngeneic model, which showed superior tumor growth inhibition and reduced lung metastasis comparable to existing drugs such as Olaparib and anti-PD1." (PMID 36235254, 2022). "Interestingly, over-expression of ENPP1 was also reported in M2 macrophages, which play an important role in tumor progression." (PMID 36235254, 2022). "However, 2′,3′-cGAMP as a STING stimulator is easily recognized and degraded by ecto-nucleotide pyrophosphatase/phosphodiesterase 1 (ENPP1), which reduces the effect of tumor immunotherapy and promotes metastatic progression." (PMID 35806118, 2022).
tumor (continued). "However, 2′,3′-cGAMP, as a STING stimulator, is easily recognized and degraded by ecto-nucleotide pyrophos-phatase/phosphodiesterase 1 (ENPP1), which weakens the effect of tumor immunotherapy." (PMID 35806118, 2022). "Furthermore, compound 4e was investigated in cytotoxicity studies and pharmacological research in vivo, indicating that compound 4e can be used as a novel drug candidate targeting ENPP1 for tumor immunotherapy." (PMID 35806118, 2022). "As ENPP1 levels modulate 2′3′-cGAMP levels and therefore affect its anti-tumor activity, we speculated the involvement of ENPP1 in EMT modulation as well." (PMID 36235254, 2022). "In this experiment, we studied whether ectopic over-expression of ENPP1 in MCF7 tumor cells could cross-reactivate TCR-Ts." (PMID 32395117, 2020). "In addition, a cGAMP hydrolase, ENPP1, was identified as a tumor-expressed surface and secreted enzyme to clear extracellular cGAMP as a means of preventing activation of innate immune cells." (PMID 33520994, 2020). "ENPP1 inhibitor could synergize with radiation to enhance immune-mediated tumor rejection by increasing cGAMP availability in the tumor microenvironment." (PMID 33520994, 2020). "We hypothesize that by conditionally enhancing STING activation, ENPP1 inhibitors will facilitate development of anti-tumor cellular immune responses, particularly following radiation therapy." (PMID 30400822, 2018). "Moreover, our data reveal that all ENPP1‐carrying exosomes extracted from tumor tissues can effectively degrade 2′3′‐cGAMP, which suggests that tumor‐derived exosomes are likely to hydrolyze 2′3′‐cGAMP in the tumor microenvironment by surface ENPP1 and dampen immune detection." (PMID 38498770, 2024). "In this work we identify that while cancer cells may not express Enpp1, cells of the tumor stroma in particular tumor-associated macrophages express Enpp1." (PMID 39622844, 2024). "However, besides the ENPP1 protein distributed on the tumor cell membrane, it remains unknown whether other forms of ENPP1 protein that can hydrolyze 2′3′‐cGAMP are present in the tumor microenvironment." (PMID 38498770, 2024). "However, in studying the role of Enpp1 in anti-tumor immune responses, we observed that Enpp1 expression is inconsistent between tumor types, suggesting that Enpp1 targeted inhibitors may have restricted application." (PMID 39622844, 2024). "In the absence of cancer-cell associated Enpp1, degradation of cGAMP released from the cancer cells may be impacted by the presence of Enpp1-expressing macrophages in the tumor immune environment." (PMID 39622844, 2024). "Furthermore, ENPP1 was detected in exosomes derived from various mouse tumor cells, which indicates that ENPP1 may be expressed widely in tumor‐derived exosomes." (PMID 38498770, 2024). "Indeed, tumor exosomal ENPP1 may have a strong degradation activity for any form of 2′3′‐cGAMP, thus inhibiting cGAS‐STING signaling." (PMID 38498770, 2024). "A relevant role of ENPP1 in tumor development could already be seen in mouse in vivo studies." (PMID 38022587, 2023). "Moreover, they reported a series of potent ENPP1 inhibitors that could delay tumor growth in a metastatic breast cancer mouse model due to increasing endogenous cGAMP." (PMID 35806118, 2022). "Finally, we found that since compound 4e could enhance the expression levels of IFN-β in vivo by preventing cGAMP from degrading due to ENPP1, it might be applied in tumor immunotherapy." (PMID 35806118, 2022). "In conclusion, we comprehensively analyzed the relationship between ENPP1 expression and HRD score across pan-cancer samples from 33 tumor types, which, to our knowledge, represents the first report on a pan-cancer scale." (PMID 41496120, 2026). "We analyzed the relationship between ENPP1 expression and HRD score across the Cancer Genome Atlas pan-cancer and individual tumor types using the Pearson and Spearman correlations." (PMID 41496120, 2026).